IL17A (interleukin 17A)
Description:
Effector cytokine of innate and adaptive immune system involved in antimicrobial host defense and maintenance of tissue integrity. Signals via IL17RA-IL17RC heterodimeric receptor complex, triggering homotypic interaction of IL17RA and IL17RC chains with TRAF3IP2 adapter. This leads to downstream TRAF6-mediated activation of NF-kappa-B and MAPkinase pathways ultimately resulting in transcriptional activation of cytokines, chemokines, antimicrobial peptides and matrix metalloproteinases, with potential strong immune inflammation. Plays an important role in connecting T cell-mediated adaptive immunity and acute inflammatory response to destroy extracellular bacteria and fungi. As a signature effector cytokine of T-helper 17 cells (Th17), primarily induces neutrophil activation and recruitment at infection and inflammatory sites (By similarity). In airway epithelium, mediates neutrophil chemotaxis via induction of CXCL1 and CXCL5 chemokines (By similarity). In secondary lymphoid organs, contributes to germinal center formation by regulating the chemotactic response of B cells to CXCL12 and CXCL13, enhancing retention of B cells within the germinal centers, B cell somatic hypermutation rate and selection toward plasma cells (By similarity). Effector cytokine of a subset of gamma-delta T cells that functions as part of an inflammatory circuit downstream IL1B, TLR2 and IL23A-IL12B to promote neutrophil recruitment for efficient bacterial clearance (By similarity). Effector cytokine of innate immune cells including invariant natural killer cell (iNKT) and group 3 innate lymphoid cells that mediate initial neutrophilic inflammation (By similarity). Involved in the maintenance of the integrity of epithelial barriers during homeostasis and pathogen infection. Upon acute injury, has a direct role in epithelial barrier formation by regulating OCLN localization and tight junction biogenesis (By similarity). As part of the mucosal immune response induced by commensal bacteria, enhances host's ability to resist pathogenic bacterial and fungal infections by promoting neutrophil recruitment and antimicrobial peptides release (By similarity). In synergy with IL17F, mediates the production of antimicrobial beta-defensins DEFB1, DEFB103A, and DEFB104A by mucosal epithelial cells, limiting the entry of microbes through the epithelial barriers (By similarity). Involved in antiviral host defense through various mechanisms (By similarity). Enhances immunity against West Nile virus by promoting T cell cytotoxicity (By similarity). May play a beneficial role in influenza A virus (H5N1) infection by enhancing B cell recruitment and immune response in the lung (By similarity). Contributes to influenza A virus (H1N1) clearance by driving the differentiation of B-1a B cells, providing for production of virus-specific IgM antibodies at first line of host defense (By similarity).
Synonyms: IL-17; IL-17A; CTLA-8; CTLA8; IL17; ILA17
Tractability: Small molecule: a structure with a bound ligand is known; a high-quality ligand is known. Antibody: an approved drug acts on it; UniProt places it where antibodies can reach, with high confidence; its Gene Ontology location is reachable by antibodies, with high confidence; UniProt predicts a signal peptide or a membrane-spanning region. PROTAC: a small molecule that binds it is known. Other modalities: a drug acting on it is in phase 2 or 3 trials.
Target class: Secreted protein
Gene: Protein-coding gene on chromosome 6 (52,186,375 to 52,190,638, forward strand). Ensembl gene ENSG00000112115.
Subcellular location: Secreted
Pathways (Reactome):
Immune System: Interleukin-17 signaling; Interleukin-4 and Interleukin-13 signaling
Disease: SARS-CoV-2 activates/modulates innate and adaptive immune responses
Gene Ontology:
Molecular function: cytokine activity; protein binding; protein heterodimerization activity; protein homodimerization activity
Biological process: fibroblast activation; interleukin-17-mediated signaling pathway; interleukin-17A-mediated signaling pathway; positive regulation of chemokine (C-X-C motif) ligand 1 production; positive regulation of cytokine production involved in inflammatory response; positive regulation of interleukin-1 beta production; positive regulation of interleukin-12 production; positive regulation of interleukin-16 production; positive regulation of interleukin-23 production; positive regulation of interleukin-6 production; positive regulation of osteoclast differentiation; positive regulation of transcription by RNA polymerase II; positive regulation of tumor necrosis factor production; response to wounding; apoptotic process; cell death; cell-cell signaling; immune response; inflammatory response; protein K63-linked ubiquitination; T-helper 17 type immune response; defense response to fungus; defense response to Gram-negative bacterium; defense response to Gram-positive bacterium; gene expression; and 9 more
Cellular component: extracellular region; plasma membrane; external side of plasma membrane
Genetic constraint (gnomAD): Loss-of-function variants: 5 observed, 13.55 expected, observed/expected ratio (o/e) 0.37, 90% interval 0.19 to 0.78. The upper end of that interval is the gene's LOEUF score, 0.78, which puts it in group 3 of 6, group 1 being the genes least tolerant of losing a copy. Missense variants: 191 observed, 208.31 expected, observed/expected ratio (o/e) 0.92, 90% interval 0.81 to 1.03. Synonymous variants: 90 observed, 81.54 expected, observed/expected ratio (o/e) 1.1, 90% interval 0.93 to 1.32.
Homologues: Orthologues: chimpanzee IL17A (99% identical), macaque IL17A (97% identical), rabbit IL17A (75% identical), pig IL17A (74% identical), guinea pig IL17A (68% identical), mouse Il17a (63% identical), rat Il17a (60% identical), Caenorhabditis elegans F25D1.3 (19% identical). Paralogues in human: IL17F (45% identical), IL17C (30% identical), IL17B (25% identical), IL17D (25% identical), IL25 (20% identical).
Diseases named in the same sentence as IL17A in open-access papers:
IL17A is named in the same sentence as 1,337 diseases in open-access papers, as found by Europe PMC text mining. Sharing a sentence is not in itself a finding about the gene and the disease. The quoted sentences say what the papers report.
psoriasis (2,800 papers, 2009 to 2026). An autoimmune condition characterized by red, well-delineated plaques with silvery scales that are usually on the extensor surfaces and scalp. "Monoclonal antibodies designed to target IL-17A, IL-17F, IL-17RA, and IL-23 have been authorized for clinical use in treating IL-17-associated autoimmune disorders, such as psoriasis." (PMID 40536951, 2026). "Nonetheless, clinical trials have demonstrated that secukinumab, an IL-17A inhibitor that is effective in treating psoriasis and PsA, is associated with the onset or exacerbation of IBD, including Crohn’s disease and ulcerative colitis." (PMID 40536951, 2026). "Its mechanism of action involves dual inhibition of interleukin (IL)-17A and IL-17F, which are implicated in IL-23-dependent and IL-23-independent psoriasis." (PMID 41551623, 2026). "For example, a recent report described a psoriasis patient who experienced severe DM flares associated with secukinumab (IL-17A inhibitor) treatment." (PMID 40861474, 2025). "Simultaneously, IDMF represses pro-inflammatory transcription factors, including NF-κB, AP-1, and potentially IRF1, leading to the downregulation of key psoriasis-associated cytokines such as IL-17A, IL-23A, IL-36G, and IFN-γ." (PMID 41465291, 2025). "In psoriasis, tapinarof reduces the levels of key pathogenic cytokines, including IL-17A, IL-17F, IL-22, and IL-23." (PMID 40162433, 2025). "Unlike, IL-1β that is constitutively expressed in human keratinocytes, IL-36 cytokines are expressed at low levels but are strongly upregulated in response to infection and psoriasis-associated cytokines, including IL-17A." (PMID 40121229, 2025). "Their findings demonstrate that secukinumab effectively cleared psoriasis skin lesions by reducing the expression levels of several lymphatic cytokines involved in the inflammatory cascade response associated with IL-17A." (PMID 39996178, 2025). "TNF-α is instrumental in the IL-23/IL-17 axis, working in synergy with IL-17A to regulate cytokines and keratinocyte-associated genes involved in psoriasis." (PMID 40303401, 2025). "To confirm the results obtained by RNA‐seq, we performed qPCR to detect and quantify CXCL1, CXCL2, CXCL8, CSFR3, OSM and TREM1, in addition to the psoriasis‐associated genes IL‐17A and IL‐23." (PMID 40181552, 2025). "In conclusion, more investigation needs to be conducted to clarify the mechanisms in which IL-17A causes psoriasis, which will contribute to the creation of innovative remedies." (PMID 40303401, 2025). "Specifically, studies have found that Ligilactobacillus and Anaeroplasma correlate positively with psoriasis-associated cytokines IL-6, IL-17A, IL-22, and IL-23, while Rikenella, Alistipes, and Mucispirillum are negatively correlated." (PMID 40161116, 2025). "IL-17a and IL-23 are two cytokines closely associated with the pathogenesis of autoimmune diseases, including psoriasis." (PMID 40557155, 2025). "The pathogenic role of CD8+ T cells in psoriasis, characterized by the release of cytokines such as IL17A and IL22, has been extensively elucidated." (PMID 41162356, 2025). "The production of tumor necrosis factor-alpha (TNFα), interferon-gamma (IFNγ), and IL-8 is promoted around this IL-23/IL-17 A system, which is thought to cause a chain reaction of psoriasis exacerbations." (PMID 40481552, 2025). "IL-17A is linked to prolonged disease duration and increased inflammatory cytokine production in psoriasis." (PMID 39996178, 2025). "Globally, IL-17A and IL-17A/F modulated the expression of proliferation, differentiation, and psoriasis-associated markers." (PMID 40243580, 2025). "Bimekizumab, however, represents a novel therapeutic approach by dual inhibition of IL-17A and IL-17F, which are both implicated in the pathophysiology of psoriasis." (PMID 40807042, 2025).
psoriasis (continued). "The analysis of the link between psoriasis and CSU in patients treated with the IL-17A blocker ixekizumab indicates that while this treatment is effective for psoriasis, it can cause urticaria in about 8.8% of patients." (PMID 39859462, 2025). "AhRs are involved in gene expression regulation, and their activation leads to the inhibition of pro-inflammatory pathways implicated in psoriasis (Th17 pathway; cytokines: IL-17A, IL-17F)." (PMID 40109802, 2025). "IL-17A was a crucial factor associated with abnormally upregulated Wnt5a expression during psoriasis development." (PMID 40365308, 2025). "Conversely, blocking IL-17A signaling via its receptor (e.g., through Brodalumab therapy) has been linked to adverse psychiatric outcomes, including increased suicide risk, in psoriasis patients." (PMID 40649841, 2025). "In psoriasis, T cell activity, specifically T helper 17 (Th17) cells, is implicated in the disease process through the secretion of proinflammatory cytokines interleukin-17A (IL-17A) and IL-22." (PMID 39866422, 2025). "Numerous studies conducted over the last ten years have highlighted the significant function of IL-17A in regulating the adaptive as well as innate immune responses, distinguishing it as an imperative cytokine associated with the etiology of psoriasis and PsA." (PMID 40303401, 2025). "IL-17A and IL-17F are particularly implicated in psoriasis signaling, forming two homodimers and the IL-17A/F heterodimer." (PMID 38258121, 2024). "Further analysis revealed that the IL-17A-producing CD8+ TRM cells are associated with early relapse of psoriasis after therapy." (PMID 38642273, 2024). "Concurrently, this demonstrates that APLNs used in treating IMQ-induced mouse psoriasis can mitigate skin psoriasis in mice through the diminished levels of cytokines associated with psoriasis, including IL-17F, IL-22, and IL-17A etc." (PMID 39534602, 2024). "Psoriasis is a systemic disease induced by various factors, in which the IL-17A pathogenic axis playing a crucial role." (PMID 38185620, 2024). "Expression of IL-22 is often associated with inflammatory skin conditions, such as psoriasis, where it is often co-expressed with IL-17A." (PMID 38543790, 2024). "Consistent with the fact that IL-17 has a pathogenic role in psoriasis by inducing pro-inflammatory molecules, treatment with an anti-IL-17A antibody, such as secukinumab, has shown sustained efficacy in psoriatic arthritis." (PMID 39273036, 2024). "ILC3s are primarily found in the intestine and skin and are considered to play a pathogenic role in psoriasis by producing IL-17A and IL-22." (PMID 38347543, 2024). "Anti-inflammatory therapies not only hold a pivotal position in the management of psoriasis but also can mitigate the risk of cardiovascular diseases by decreasing inflammatory markers such as IL-17A." (PMID 39104857, 2024). "The success of these treatments underscores the therapeutic relevance of IL-17A in psoriasis and its potential as a target in other IL-17A-associated diseases." (PMID 38892253, 2024). "IL-17A and IL-17F levels have been linked to chronic inflammatory diseases, such as psoriasis, multiple sclerosis, systemic lupus erythematosus, rheumatoid arthritis, and juvenile idiopathic arthritis." (PMID 39931580, 2024). "Central to psoriasis pathogenesis is the dysregulated signaling of cytokines influencing pathogenic immune responses, particularly IL-23 and IL-17A." (PMID 38975347, 2024). "IL‐17A, as an important pathogenic factor in psoriasis, contributes to its critical role in mediating systemic inflammation and depression comorbidity." (PMID 39660880, 2024). "Alterations in LCFAs of IMQ-treated WT and Tcrd−/− mice suggest a potential association between the pivotal pathogenic factor IL-17A and the abnormal metabolism of LCFAs among psoriasis patients." (PMID 38185620, 2024).
psoriasis (continued). "Ongoing research and clinical trials are crucial to further elucidate the efficacy and safety of IL-17A inhibitors, potentially paving the way for novel therapeutic strategies that integrate the management of psoriasis and cardiovascular risk." (PMID 38892457, 2024). "Interleukin-17F (IL-17F) is another member of the IL-17 cytokine family that, like IL-17A, has been implicated in the pathogenesis of psoriasis." (PMID 38541607, 2024). "In light of this, therapies targeting IL-17A have garnered attention for their potential to not only manage psoriasis, but also to mitigate associated vascular inflammation that can lead to serious cardiovascular events." (PMID 38892457, 2024). "Group 3 innate lymphoid cells lack rearranged antigen-specific receptors, rely on the transcription factor RORγt, and respond to IL-1β and IL-23; a subset of group 3 innate lymphoid cells is associated with production of IL-17A and IL-22 in psoriasis lesions." (PMID 39114670, 2024). "Several studies in clinical research have demonstrated that the use of interleukin (IL)-17A inhibitors in treating psoriasis also contributes to a reduction in cardiovascular risk among patients with this condition." (PMID 39104857, 2024). "The data show that inhibition of IL-17A improves psoriasis-associated complications, such as atherosclerosis." (PMID 39519167, 2024). "The TH1/TH17 axis is widely recognized for its significant involvement in the pathogenesis of psoriasis, with the progression of atherosclerosis being closely linked to the secretion of IL-17A by TH17 cells." (PMID 39219794, 2024). "It proved highly effective in alleviating psoriasis manifestation by eliminating the pathogenic factor IL-17A." (PMID 38396109, 2024). "In the present study, IMQ‐induced psoriasiform dermatitis mice presented typical psoriatic pathological characters and obviously elevated IL‐17A serum levels, which further confirmed the pathogenic effects of IL‐17A in the pathogenesis of psoriasis." (PMID 39660880, 2024). "Among them, IL-17A and IL-23 have emerged as pivotal pathogenic molecules in psoriasis, and immunomodulation with biologics aimed at targeting them has resulted in substantial improvement in the disease symptoms and quality of life for patients." (PMID 38929716, 2024). "The humanized monoclonal antibody ixekizumab is designed to target and suppress the production of IL-17A, a cytokine associated with autoimmune conditions such as psoriasis and psoriatic arthritis." (PMID 38605952, 2024). "Nevertheless, the overall effect of IL-17A in cardiovascular comorbidity associated with psoriasis is still partially unclear." (PMID 37953417, 2024). "On the other hand, an exploratory post hoc analysis revealed that psoriasis patients experienced weight loss after 52 weeks of IL-17A treatment." (PMID 38185620, 2024). "Mechanistic investigations revealed that miR-26a-5p induced a cascade of downregulated genes associated with the IL-23/IL-17A axis, which is known to be critical in psoriasis pathogenesis, while concomitantly suppressing CDC6 and CCNE1 expression." (PMID 38446584, 2024). "IL17A is vital for pathogen defense, but elevated levels are associated with various inflammatory and autoimmune conditions, including psoriasis, rheumatoid arthritis, and MASLD." (PMID 39459627, 2024). "Psoriasis is an immune‐mediated chronic inflammatory skin disease, in which T helper 17 (Th17) cells and its effective cytokine interleukin (IL)‐17A play a pivotal pathogenic role." (PMID 38414294, 2024). "Conversely, low plasma IL-17A levels were linked to an increased incidence of cardiovascular diseases in patients with moderate-to-severe psoriasis." (PMID 38392619, 2024). "Their study revealed that the topical application of compound 3 (2 mM) significantly ameliorated hyperplasia and inflammatory cell infiltration and suppressed the expression of the psoriasis-associated genes S100a9, Krt1, Il17a, and Il22." (PMID 37111813, 2023).